RAG2 (recombination activating 2)
Diseases named in the same sentence as RAG2 in open-access papers (continued):
Sharing a sentence is not in itself a finding about the gene and the disease.
infection (continued). "Consequently, piglets carrying homozygous RAG1, RAG2, or IL2RG mutations (A632-2, A632-1), which looked normal and strong upon birth, died 12 and 49 days after birth, respectively, due to infection in the lung." (PMID 31253764, 2019). "In Rag2–deficient C57BL/6 mice, 5ASKH infection caused progressive lesion development." (PMID 31738761, 2019). "In order to determine whether KSHV-associated BCR revision was Rag-mediated we performed nested RT-PCR for Rag transcripts and were able to detect both RAG1 and RAG2 mRNA at early time points post-infection." (PMID 29659614, 2018). "Pathology of spontaneous infection by E. coli in Rag2 and Il2rγ knockout Wsh/Wsh mice." (PMID 29554148, 2018). "Finally, we tested the capacity of Mtb-infected pHSCs of human LTBI and of mice 28 days p.i. to resuscitate active infection upon intratracheal application into the trachea of Rag2–/–Il2rg–/–mice." (PMID 28046053, 2017). "In contrast to wild type (WT) B6 mice, immunodeficient Recombination activating gene 2 (Rag2) knockout mice showed no signs of infection-associated changes in HSPCs, despite a significantly higher parasite burden." (PMID 28671989, 2017). "Eventually, the infected RAG2−/− mice succumbed to infection after day 20 p.i." (PMID 28874800, 2017). "No death were observed in both immunocompetent SD and immunodeficient Rag2-/- rats after infection, and systemic histopathology examination was performed for many tissues including brain stem, cerebellum, mouth, heart, liver, spleen, lung, kidney, intestine, testis and ovary." (PMID 26235050, 2015). "In the present study, at day 1 post infection of rTV-Fluc, the bioluminescence imaging of SD and Rag2-/- rats could be detected in limbs muscle, skin, ovary and brain." (PMID 26235050, 2015). "Interestingly, infection of IL-15 KO mice with the protozoan parasite Toxoplasma gondii or IL-15 KO, IL-15Rα KO, and RAG2/IL-2Rγ KO mice with MCMV infection results in rapid expansion of NK cells." (PMID 25197644, 2014). "However, at later stages of infection the adaptive immune response which is necessary to clear the virus and protect the host from lethal pathological damage is missing in Rag2-/- mice." (PMID 20667098, 2010). "Similar percentages of airways were affected in wild type and Rag2-/- mice after infection." (PMID 20667098, 2010). "Therefore, while 0--GFP infection is avirulent in rag2-/- mice, 0--GFP cannot induce protective immunity against HSV-1 in animals that lack a lymphocyte-driven adaptive immune response." (PMID 16764725, 2006). "Wild-type (ICP0+) strains of HSV-1 produced lethal infections in scid or rag2-/- mice." (PMID 16764725, 2006). "We report evaluations of two additional commercially available mouse strains, C57BL/6NTac.Cg-Rag2tm1Fwa Il2rgtm1Wjl (RAG2-/-γc-/-), and C.B-Igh-1b/IcrTac-Prkdcscid (C.B-17 SCID) with or without additional steroid treatment, for susceptibility toD. immitis tissue-phase larval infection." (PMID 39036651, 2024). "Indeed, by day 6 and 9 post-infection, while WT mice presented a 25% and 48% reduction in total fat mass, respectively, Rag2−/− mice showed no substantial loss of fat mass." (PMID 37828246, 2023). "Furthermore, analysis of gene expression changes in Rag2 mutant mice after infection and in comparison to wild type expression profiles clearly highlighted the deficiency in the T and B cell response in Rag2 mutant mice and verified the specificity and sensitivity of our analyses." (PMID 22815957, 2012). "However, at day 10 after infection necrosis was considerably more severe in Rag2-/- mice." (PMID 20667098, 2010). "Mouse analyses employed an RT-PCR CRISPR assay to analyze P. murina transcripts in WT and Rag2–/– mouse lung RNA, BAL, and serum at 2-, 4-, and 6-weeks after infection." (PMID 40029713, 2025). "Despite large variability in the experiment, we found that overall, RAG2 KO mice reconstituted with GzmA/B dKO IEL lost more weight and had a higher infection burden than RAG2 KO with WT IEL." (PMID 39137883, 2024).
infection (continued). "Parasite load in the brain of WT or RAG2 KO mice, treated with either α-IgG2 or α-ICAM1 antibody, quantified by intravital microscopy, at day 6 post-infection." (PMID 35787830, 2022). "Quantitative real-time PCR analysis of key inflammatory mediators demonstrated that SARS-CoV-2 (MA10) infection elevated cytokine IL-6 in BLAB/c and chemokine Ccl2 expression in Rag2−/− mice in comparison with mock-treated mice." (PMID 36680154, 2022). "We therefore infected a Rag2-/- mouse with the clinical isolate CCHFV strain Hoti by the intraperitoneal (IP) route and for the first passage collected blood at 4 weeks post-infection (WPI)." (PMID 33416494, 2021). "In the Rag2-Il2rg double-knockout mice transplanted with CD133-negative HepG2 cells, the AFP secretion in the mouse serum after paOAd infection was significantly decreased by blue light irradiation." (PMID 32703933, 2020). "This infection protocol was found to be very efficient, as in most of the inoculated HIS Rag2-/-γc-/- mice the provirus was found integrated in the genome of human cells." (PMID 21909275, 2011). "As a preface to such studies we compared the course of CVS-F3 infection in JHD−/− and RAG-2−/− mice." (PMID 19806203, 2009). "In contrast, euthyroid Rag2-/- mice, but not hypothyroid Rag2-/- mice, presented elevated NK cells and monocytes after infection." (PMID 41263555, 2025). "We found that Rag2−/− mice were not susceptible to primary RSV infection but failed to fully clear the virus from their lungs and showed a long‐term infection." (PMID 40899087, 2025). "Lung tissue Sp and Gsc1 signal did not vary over time in Rag2–/– mice, but both significantly decreased at 6 weeks after inoculation in the WT mice, potentially indicating infection clearance." (PMID 40029713, 2025). "On the other hand, at day 1, when only the innate immune system is sensing the infection, hypothyroid mice show a higher degree of infection, and according to these data, RAG2-/- mice lacking adaptive immune cells are also more sensitive to VACV infection." (PMID 41263555, 2025). "Despite the absence of T cells, Rag2-/- mice exposed to LPS before RSV infection lost weight similar to WT mice undergoing the same infection regime." (PMID 39127259, 2024). "The viral load at day 4 post infection was also not significantly altered in Rag2-/- compared to WT, suggesting T cells do not reduce the viral load early during the infection in LPS exposed mice compared to RSV only mice." (PMID 39127259, 2024). "Conversely, prior PR8 infection impaired acute bacterial clearance in BALB/c WT but not Rag2-/-Il2rg-/- mice." (PMID 37771584, 2023). "Representative images of parasite sequestration in brains of WT and RAG2 KO mice with and without perfusion, at day 6 post-infection." (PMID 35787830, 2022). "We infected RAG2-/- and RAG2-/-γc-/- immunodeficient and BALB/c immunocompetent mice with B. malayi infectious larvae and examined impact on NKp46+ NK cell expansion within the peritoneal infection site." (PMID 36238293, 2022). "The study demonstrated that SARS-CoV-2 (MA10) infection did not cause any mortality in 10-week-old C57BL/6, BALB/c, and Rag2−/− mice, although there is an increase in pulmonary viral load and increased weight loss in C57BL/6, BALB/c and Rag2−/− mice." (PMID 36680154, 2022). "In contrast in B6.Rag2-/- mice, no early decline in absolute monocyte numbers was noted early after infection and a transient ~2 fold increase was observed at d28." (PMID 34557190, 2021). "However, all BALB/c RAG2−/−γc−/− infected mice (10/10 mice, 2 or 5 months post infection) and all BALB/c RAG2−/− mice implanted with adult L. loa (5/5 mice, one month post implantation) were FTS positive." (PMID 30926803, 2019). "In line with this, both RAG2−/− and IFN-γ−/− mice succumbed to infection with the nrp-comp strain." (PMID 30381350, 2018).
infection (continued). "As with many infections, NK cells respond to both type I IFN and IL-12 during Mtb infection resulting in their production of IFNγ and are critical for early survival in the mouse model as demonstrated in RAG2−/− common-γ-chain−/− and IL-12p40−/− mice." (PMID 25197644, 2014). "RAG2−/− mice infected with PbAluc did not develop ECM contrary to wild-type (WT) C57BL/6J mice which died with neurological signs 6 to 12 days post-infection." (PMID 21494565, 2011). "In this study, we first observed that RAG2−/− mice which lack T and B cells had a reduced total parasite biomass and accumulated fewer parasites in their brains during the first week of the infection but not at later time points." (PMID 21494565, 2011). "Whereas wild type mice were able to clear the virus by day 8 after infection, Rag2-/- mice did not reduce viral loads from infected lungs at any time before death." (PMID 20667098, 2010). "Survival curves showed that wild type mice did not die from the infection at the two infection doses tested whereas Rag2-/- mice died at 8-9 days p.i. after receiving the high dose and between 11 and 14 days p.i. after the low dose of infection." (PMID 20667098, 2010). "RSV‐infected Rag2−/− mice showed no symptoms of disease or chronic inflammation in the lungs and airways despite the presence of infectious virus in their lungs several months after infection." (PMID 40899087, 2025). "To test this hypothesis, we compared the outcome of Rag2-/-Ggta1-/- mice upon a systemic infection by Ig-shaped vs. a non-Ig-shaped microbiota." (PMID 34009123, 2021). "Additionally, all infection positive BALB/c RAG2−/−γc−/− mice (8/8 mice) but not infection negative RAG2−/− mice (0/9 mice) were seropositive for the distinct filarial adult antigen, Og4C3, 5 months after experimental infection (p < 0.0001, Mann–Whitney test)." (PMID 30926803, 2019). "In histological sections of lungs of the Rag2–/–Il2rg–/–mice transplanted with either human pHSCs from LTBI or mouse pHSCs from Mtb-infected mice, we observed increased cellularity in the lungs indicative of an inflammatory infiltrate in response to an active infection 3 weeks after pHSC transfer." (PMID 28046053, 2017). "Furthermore, infection of Rag2 KO mice did not deplete the reservoir of quiescent HSCs, suggesting a central role for adaptive immunity as a driver of these effects in immunocompetent mice." (PMID 28671989, 2017). "We conclude from these studies that the innate immune response, although it may not be completely normal in Rag2-/- mice, works as efficiently as in wild type mice to control viral replication and spread at early stages of the infection." (PMID 20667098, 2010). "Rag2-/- mice survived 0--GFP-infection for 60 days and exhibited no symptoms of disease." (PMID 16764725, 2006). "This requirement was enhanced in mice lacking Rag2, Ifng, or Nos2, consistent with the preferential role of ESX1 during the initial stage of infection before the initiation of adaptive immunity, which is prolonged in these immunodeficient strains." (PMID 35112666, 2022). "To further confirm that protection after GDAR2-2 colonization was independent of adaptive immunity, we treated Rag2−/− mice with ABX and left uncolonized or colonized with GDAR2-2 before infection with C. rodentium." (PMID 34989321, 2022). "In contrast, adoptively transferred Rag2 KO mice that were not infected retained their full quiescent HSPC pool, indicating that infection rather than homeostatic expansion of CD4+ T cells is required to drive LT-HSCs out of quiescence." (PMID 28671989, 2017). "Other lymphocytes, which are absent in Rag2-/- skin, such as B cells and CD8+ T cells were rare in infected skin (<1000 cells) and did not expand in number, or proportion after repeated infection, nor did they produce IL-10." (PMID 25974019, 2015).
infection (continued). "In conclusion, the present results strongly suggest that the innate immune response in Rag2-/- knock-out mice, although it may not be completely normal, works as efficiently as in wild type mice to protect the host from lethal pathologies at early time points after infection." (PMID 20667098, 2010). "However, infection-induced neutrophil migration into liver tissue was still reduced after LPS pretreatment in JHT mice, but not in Rag2-/- animals." (PMID 36178806, 2022).
cancer (45 papers, 2007 to 2026). A tumor composed of atypical neoplastic, often pleomorphic cells that invade other tissues. "Mice with a homozygous deletion of the Rag-2 alleles completely lack NK-like T, T and B cells and have increased incidence and growth of spontaneous tumors and chemically induced cancer lesions." (PMID 34202278, 2021). "This premise is supported by our previous work illustrating that Hh infection induced more invasive cancer in the lower bowel of Rag2-deficient male mice receiving Il10-deficient regulatory T cells compared to their female counterparts." (PMID 33255175, 2020). "Taken together, both the rag2 knockout animal and the protocol for irradiating wild-type froglets add a new and important tool to strengthen the application of cancer modeling in the diploid amphibian Xenopus tropicalis." (PMID 36230482, 2022). "IPA showed significant changes in the expression levels of genes associated with gastrointestinal disease (Abcb1, Guca2a, Muc2, Rag2, Itga6, and Shh), inflammatory disease (Abcb1, Muc2, and Rag2), and cancer (Muc2, Guca2a, and Rag2)." (PMID 33396408, 2020). "Apart from rag2, a number of tissue-specific promoters have been used to drive oncogene expression into transgenic zebrafish and to induce cancer formation." (PMID 32759814, 2020). "These latter cancers expressed homologues of human B-lymphoblast genes, such as rag1 and rag2, pax5, dntt (a TdT orthologue), and cd79a (aka, Ig)." (PMID 31731471, 2019). "The Rag2 KO mouse model is widely used for xenotransplantation experiments and preclinical studies of human diseases including cancers." (PMID 29495457, 2018). "Although the gross appearance of TSGs maintained in both hosts for 1 month was similar, the average graft weight and the proliferation index of cancer in RAG2−/−γc−/− mice were significantly higher than in NIH III mice." (PMID 23985008, 2013). "RAG1 and RAG2, the essential enzymes for V(D)J recombination, were also detected in cancer samples, whereas AID, an enzyme required for class switch and somatic hypermutation, was only detected in the two poorly differentiated cell lines (LOVO and HCT116)." (PMID 23133595, 2012). "Recombination activating gene 1 (RAG1) and RAG2, which are essential enzymes for initiating variable-diversity-joining segment recombination, have also been found to be expressed in cancer cells." (PMID 21655267, 2011). "However, all SK-N-AS xenografts eventually relapsed in NSG mice after 2 months of therapy, suggesting that residual disease is responsible for cancer relapse, which is eliminated in Rag2-/- mice." (PMID 40962798, 2025). "To understand the role of cancer-cell-derived PGE2 in immune evasion, we ablated PGE2 production through cyclooxygenase-1 (COX1; encoded by Ptgs1) and COX2 (encoded by Ptgs2) KO in RTT cells and engrafted them into Rag2–/– mice." (PMID 39604727, 2025). "Rag2 KO mice were selected as a suitable model for our first experiment, since this mouse strain has no mature B and T cells and is considered an excellent xenograft host for cancer cell lines." (PMID 38239393, 2023). "Exposing rag2:hMYC-ER larvae to 4HT beginning at 5 dpf caused 100% T-ALL penetrance by five weeks of age, but many cancers regressed upon 4HT withdrawal, suggesting some ‘leukemias’ were not stably transformed, but rather lymphoproliferations that relied upon very high MYC activity." (PMID 31731471, 2019). "We also confirmed the expression of RAG1 and RAG2 in these cancer cell lines." (PMID 21655267, 2011). "In this report, we characterized a Rag2, Il2rg double knockout rat model on the Sprague-Dawley strain, the SRGTM rat, and demonstrated that it is a competent host for human cancer cell lines, PDX modeling, and drug efficacy studies in oncology (SRG OncoRat®)." (PMID 33027304, 2020).
cancer (continued). "Its feasibility for detecting SLNs of the gallbladder was evaluated using a laparoscopic dual-tracer method by injecting ICG and SPIONs into five wild-type pigs without cancer and one immunodeficient (RAG2-knockout) cancer-bearing pig." (PMID 35053527, 2022). "For example, recombination-activating gene 2 (RAG2)-deficient mice that lack both T and B cells are more susceptible to spontaneous and carcinogen-induced carcinomas, while mice lacking γδT cells are highly susceptible to cutaneous carcinogenesis." (PMID 27703456, 2016). "Mice which lacked both T and B cells, due to a deficiency in the recombination-activating gene 2 (RAG2), were more susceptible to spontaneous and carcinogen-induced carcinomas." (PMID 24860567, 2014). "Further investigation into the functional relationships of RAG2 and PAX8 with cancer associated genes, especially those that are not typically expressed in the thyroid, is needed to fully understand and potentially disrupt these disease pathways using innovative therapeutic interventions." (PMID 33716974, 2021). "Although expression of Rag1 and Rag2 transcripts have been reported in a variety of non-lymphoid cells, including different cancer cell types, epithelial cells and neurons, to our knowledge, no functional role for these enzymes have been identified in non-lymphoid cells." (PMID 29755449, 2018).
inflammation (3 papers, 2011 to 2020). Aberrant reaction of the microcirculation characterized by movement of fluid and leukocytes from the blood into extravascular tissues. "H&E stained lung sections of OVA treated RAG2-/- mice demonstrated severe lung inflammation and most of the cellular infiltrate was composed of eosinophils." (PMID 22014099, 2011). "This notion is supported by the observation that NKT cells but not total spleen cells isolated from 2,4αβNOD.Rag2+/− control mice could induce liver inflammation and fibrosis when adoptively transferred to naïve NOD.Rag2−/− mice." (PMID 33311540, 2020).
bacterial infection (2 papers, 2015 to 2022). "As IL‐22‐producing group 3 ILCs protect from intestinal bacterial infection, we challenged RAG2−/− mice on eRapa or Eudragit for 1 month with the flagellated bacterium C. rodentium as described." (PMID 26315673, 2015). "Strikingly, the absence of lymphocytes, as in Rag2 deficient (Rag2-/-) animals, already resulted in profoundly reduced liver damage upon bacterial infection of naïve, sensitive mice and fully abrogated further LPS-induced tissue protection without affecting the bacterial load." (PMID 36178806, 2022).
hematopoietic neoplasms (1 paper, 2024). "However, in RAG1/RAG2-deficient patients, as well as in overall SCID patients, hematopoietic neoplasms are extremely rare." (PMID 39026935, 2024).
kidney disease (1 paper, 2018). "The genetic profile of the Rag2 and Il2rγ knockout Wsh/Wsh mice predisposes them to progressive kidney disease." (PMID 29554148, 2018).